TMEM123 (transmembrane protein 123)
Description:
Implicated in oncotic cell death, characterized by cell swelling, organelle swelling, vacuolization and increased membrane permeability.
Synonyms: KCT3; PORIMIN; PORMIN
Tractability: Antibody: UniProt predicts a signal peptide or a membrane-spanning region.
Gene: Protein-coding gene on chromosome 11 (102,396,332 to 102,470,384, reverse strand). Ensembl gene ENSG00000152558.
Subcellular location: Membrane
Subcellular location (Human Protein Atlas): Golgi apparatus; Cytosol; Vesicles
Gene Ontology:
Molecular function: protein binding; signaling receptor activity
Cellular component: external side of plasma membrane; cytoplasmic vesicle; membrane
Genetic constraint (gnomAD): Loss-of-function variants: 16 observed, 18.22 expected, observed/expected ratio (o/e) 0.88, 90% interval 0.59 to 1.33. The upper end of that interval is the gene's LOEUF score, 1.33, which puts it in group 5 of 6, group 1 being the genes least tolerant of losing a copy. Missense variants: 313 observed, 253.81 expected, observed/expected ratio (o/e) 1.23, 90% interval 1.12 to 1.35. Synonymous variants: 118 observed, 93.37 expected, observed/expected ratio (o/e) 1.26, 90% interval 1.09 to 1.47.
Homologues: Orthologues: chimpanzee TMEM123 (99% identical), macaque TMEM123 (93% identical), dog TMEM123 (52% identical), rat Tmem123 (50% identical), mouse Tmem123 (50% identical), tropical clawed frog tmem123 (36% identical), Drosophila melanogaster vsg (26% identical), zebrafish tmem123 (19% identical). Paralogues in human: CD164 (22% identical), CD164L2 (14% identical).
Diseases named in the same sentence as TMEM123 in open-access papers:
TMEM123 is named in the same sentence as 11 diseases in open-access papers, as found by Europe PMC text mining. Sharing a sentence is not in itself a finding about the gene and the disease. The quoted sentences say what the papers report.
viral infection (2 papers, 2021). "Finally, dSpace analysis identified several genes (CCL2, OASL, CASP7, TMEM123, MAFB, VRK2, UBE2L6, NAPA) higher in patients with mild viral infection than those with severe viral infection or HCs." (PMID 33765435, 2021). "Interestingly, TMEM123 did not significantly inhibit HIV-1 virion attachment to target cells, although it inhibited viral infection." (PMID 34064525, 2021).
breast carcinoma (1 paper, 2017). "A fusion of the same two genes has been reported in a breast carcinoma, while in one ovarian carcinoma TMEM123 was found fused with MMP7." (PMID 28893231, 2017).
lung carcinoma (1 paper, 2017). "Gene ontology analysis of these affected genes revealed TMEM123 might induce cell death in JFK treated lung cancer A549 cells." (PMID 29234412, 2017).
schizophrenia (1 paper, 2025). A major psychotic disorder characterized by abnormalities in the perception or expression of reality. "Our research found that the expression of TMEM123 in patients with schizophrenia is significantly higher than in the HC group, but there is currently insufficient evidence to support its reliability and specificity as a biomarker." (PMID 40242178, 2025). "In our study, a ceRNA network was constructed through LY96 and TMEM123, indicating that this regulatory network plays a role in schizophrenia, which provides direction and evidence for further elucidating the mechanisms of these biomarkers in SCZ." (PMID 40242178, 2025).
tumor (6 papers, 2022 to 2025). "Transmembrane protein 123 (TMEM123) can cause cancer cell swelling, cancer cell organelle swelling, vacuolization, and increased membrane permeability, thus participating in the death of tumor cells." (PMID 35186732, 2022). "We propose an active role for TMEM123 in the anti-cancer activity of T cells within tumour microenvironment." (PMID 37426665, 2023). "In this study we decided to primarily focus our attention on tumor-infiltrating T lymphocytes expressing TMEM123." (PMID 37426665, 2023). "We discovered that the protein TMEM123 is over-expressed in tumour-infiltrating CD4 and CD8 T lymphocytes and it contributes to their effector phenotype." (PMID 37426665, 2023). "In the majority of patients tested by FACS (78%) TMEM123 had a higher expression in tumor-infiltrating CD8+ than in CD4+." (PMID 37426665, 2023). "TMEM123 expression was found in both tumor-infiltrating CD8+ (19% ± 3%) and CD4+ (11% ± 2%) T cells, while it was almost undetectable in T lymphocytes isolated from normal tissues (2.7% ± 0.5%) or PBMCs (0.9% ± 0.2%)." (PMID 37426665, 2023). "To further investigate the distribution of TMEM123 nanoscale organization in CD3 T cells after stimulation with tumor CM, we used super-resolution STED microscopy." (PMID 37426665, 2023). "The DEG analysis between tumor and normal tissues showed the expression of TMEM123 was significantly increased in tumor-infiltrating T cells, which was consistent with the analysis of bulk transcriptomic outcomes." (PMID 37265785, 2023). "Research indicates that TMEM123 can induce tumor-like cell death in Jurkat cells." (PMID 40242178, 2025). "We focused our interest on TMEM123 expression in tumor-infiltrating CD8+ T lymphocytes." (PMID 37426665, 2023). "Due to the relevance of tumor-infiltrating T lymphocytes in the anti-cancer immune response, we further assessed TMEM123 expression in CD8+ and CD4+ T lymphocytes infiltrating CRC tissues by multiple immunofluorescence confocal microscopy on cryopreserved CRC tissues (N=4 samples)." (PMID 37426665, 2023). "Moreover, we investigated whether TMEM123 expression was evenly distributed among tumor-infiltrating immune cells or was enriched in specific ones." (PMID 37426665, 2023). "Furthermore, we observed TMEM123 positive staining in immune cells surrounding the tumor." (PMID 37426665, 2023). "As to better confirm TMEM123 role in CD8+ T cell migration in a more complex milieu, mimicking cancer microenvironment, we employed a human tumor organoid model, better simulating architecture of cancer tissues than cancer cell line monolayers." (PMID 37426665, 2023). "Overall the CRISPR data indicate that the 11q22.2 amplification residing genes YAP1, TMEM123, BIRC2-3 are essential for VU1365-T tumor cells vitality." (PMID 34997070, 2022). "Additionally, numerous studies have shown that TMEM123 and TMEM66 in T cells, and TMEM208, TMEM59, and TMEM258 in B cells, are closely related to inflammatory response and participate in tumor immune response, which is consistent with our findings." (PMID 37265785, 2023). "Next, we tested whether the expression of TMEM123 responded to T-cell receptor (TCR) activation via anti-CD3/CD28 T cell activation and to tumor microenvironmental stimuli known to affect fates and intrinsic pathways of T lymphocytes, relevant for trafficking, differentiation and function." (PMID 37426665, 2023). "Interestingly, TMEM123 is clearly expressed in tumor-infiltrating immune cells of the same cancer tissues, independent of its expression in cancer cells, suggesting that expression of TMEM123 is not intertwined in the two compartments." (PMID 37426665, 2023). "In addition, we believe that TMEM123 may be an attractive target for CD8+ based immunotherapy, for the design of molecular agonists able to promote the recruitment of T cells to the tumor site and attack of cancer cells, mediating anti-cancer Th1 immune responses." (PMID 37426665, 2023).
cancer (5 papers, 2011 to 2023). A tumor composed of atypical neoplastic, often pleomorphic cells that invade other tissues. "As data indicate important effects of TMEM123 on the migration of T cells, we further investigated the interplay between TMEM123+ TILs and cancer cells in co-culture assays." (PMID 37426665, 2023). "Using tumoroid-lymphocyte co-culture assays, we found that lymphocytes form clusters through TMEM123, anchoring to cancer cells and contributing to their killing." (PMID 37426665, 2023). "TMEM123 labelling tended to disappear from T cell surface soon after their detachment from cancer cells, as TMEM123-labelled protein was internalized in the cytosol, a process that appeared to be slightly faster in CD8+ than in CD4+ T cells." (PMID 37426665, 2023). "To better appraise the frequency of TMEM123 positive lymphocytes in relation to cancer progression, we carried out a multiple immunofluorescence staining on a FFPE tissue microarray containing other two sets of clinical samples." (PMID 37426665, 2023). "At present, the absence of a proof-of-principle animal model pushed us to propose the tridimensional tumoroid models to test the anti-cancer cytotoxic activity of TMEM123+ CD8 T lymphocytes." (PMID 37426665, 2023). "Our data indicate that TMEM123 is a novel component of T cell protrusions where it plays a key role in clustering of T cell on cancer cells and contributes to T cell effector functions." (PMID 37426665, 2023). "The inhibition of SMAD2 protein in the highly glycosylated signaling pathway stimulated by receptor TMEM123 can regulate the anti-apoptosis ability of cancer cells." (PMID 35164166, 2022). "In the first half of the monitoring period, the absolute number of TMEM123+ CD8+T cells interacting with cancer cells was slightly higher than TMEM123+ CD4+ T cells (up to 1.6-fold at 24h), whereas afterwards both cell types reached a plateau with comparable numbers." (PMID 37426665, 2023). "Furthermore, both in vitro CD3/CD28 activation and incubation with cancer cells conditioned medium, was enough to induce the expression of TMEM123 in peripheral T cells." (PMID 37426665, 2023). "Indeed, we observed a clear effect of TMEM123 in helping the directed migration and adhesion of lymphocytes to tumoroids, finally leading to efficient killing of cancer cells in a 3D context." (PMID 37426665, 2023). "Finally, our study provides novel evidence on the role of TMEM123 in the interaction between effector T cells and cancer cells." (PMID 37426665, 2023). "Overall, these data further confirm that TMEM123 drives T cell migration and clustering and contributes to the killing activity of CD8+ T lymphocytes on cancer cells." (PMID 37426665, 2023). "By co-culturing experiments, we found that TMEM123 localizes in anchoring sites of CD8+ T cells attacking the cancer cells and forming clusters of lymphocytes on their surface, indicating that TMEM123 plays an important role in TILs adhesion to cancer cells." (PMID 37426665, 2023). "In line with this, co-cultures of TMEM123+ CD8+ T lymphocytes with CRC tumoroids further demonstrated that TMEM123 expression is required for the directional migration of CD8+T cells towards the organoid, which is pivotal for further attacking and eliminating the cancer cells." (PMID 37426665, 2023). "Interestingly, we found that TMEM123 positivity in cancer cells did not correlate with positivity of infiltrating immune cells (Rho=0.09)." (PMID 37426665, 2023). "The copy number derived expression of 11q22.1-2 amplification resident genes was also observed in a broader cancer context; the TCGA sporadic HNSCC copy number—expression correlation data also showed significant positive correlations, most strongly in YAP1, BIRC2 and TMEM123." (PMID 34997070, 2022). "Consequently, it is not clear whether mouse cancer models may represent a valid model to study TMEM123 function in the TME." (PMID 37426665, 2023).
cancer (continued). "Finally, we assessed expression of TMEM123 by FACS analysis in CD4+ and CD8+ T lymphocytes isolated ex vivo from paired cancerous and non-tumoral tissue samples (proximal, but not adjacent to cancer cells) (N=14) and from peripheral blood (N=11)." (PMID 37426665, 2023).
infection (1 paper, 2025). The state of being infected such as from the introduction of a foreign agent such as serum, vaccine, antigenic substance or organism. "In contrast, other molecules (VCAM-1, EPHB1, TMEM123, etc.)showed little inhibitory effect on infection within the density range we used." (PMID 41147561, 2025).
TMEM123 also shares sentences with these, for which no sentence is quoted: colorectal cancer (2 papers); clubfoot (1); metastatic cancers (1); ovarian carcinoma (1).